IL6 (interleukin 6)
Diseases named in the same sentence as IL6 in open-access papers (continued):
Sharing a sentence is not in itself a finding about the gene and the disease.
mastitis (continued). "In LPS-induced mastitis, increased levels of TNF-ɑ and IL-6 in the mammary gland were observed in a previous study." (PMID 35173767, 2021). "The levels of IL-1β, IL-6, and TNF-α were significantly higher with treatment, indicating that the cell model of mastitis had been successfully established." (PMID 34575880, 2021). "They found higher serum levels of IL-1β and IL-2, TNF-α, IL-6, and IFN-γ in subclinical mastitis compared to control cows." (PMID 34484387, 2021). "The RT-qPCR technique detected the mRNA expressions levels of TNF-α, IL-6, and IL-1β to evaluate the effects of L. plantarum KLDS 1.0344 on LPS-induced mastitis using isolated bMEC." (PMID 34858427, 2021). "LPS can increase the expression of IL-6, TNF-α, and IL-1β in the mammary glands of dairy cows, which leads to the occurrence and development of mastitis." (PMID 32397071, 2020). "Real-time (RT)-PCR showed that, compared with those in the healthy dairy cows, the mRNA levels of IL-6, TNF-α, and IL-1β in the mastitis dairy cows increased significantly." (PMID 32397071, 2020). "Previous studies have proved that reducing the production of proinflammatory cytokines, such as IL-1β, IL-6, and TNF-α, can reduce the effect of mastitis." (PMID 33488936, 2020). "The suppression of IL-6 and IFN-γ usually occurs around parturition, which depresses immunity and exposes dairy cattle to mastitis." (PMID 33202860, 2020). "The expression of GPR109A, IL-6, IL-1β, and TNF-α in the mammary glands of the dairy cows with mastitis was significantly higher than it was in the glands of the healthy dairy cows." (PMID 32397071, 2020). "The mastitis indicators including clots, lactate dehydrogenase (LDH), TNF-α, IL-6, IL-8, and total viable count of bacteria (TVC) in milk were examined before and after the YXT treatment to evaluate its effectiveness." (PMID 31019541, 2019). "The inflammatory responses of mastitis at least increase SCC and levels of inflammatory cytokines, including TNF-α, IL-6, and IL-8, in milk." (PMID 31019541, 2019). "The potential targets of these high-frequency CMM in treating mastitis were intercellular adhesion molecule 1 (ICAM-1), interleukin-6 (IL-6), lipopolysaccharide binding protein (LBP), and lactotransferrin." (PMID 30911319, 2019). "In this study, TNF-α, IL-6 and IL-1β levels were significantly increased in the LPS-induced mastitis model, and peiminine inhibited the production of TNF-α, IL-6 and IL-1β in a dose-dependent manner." (PMID 30200569, 2018). "In a study where sows were experimentally inoculated with intra-mammary E. coli, elevated IL6 and TNF α was measured in inoculated sows 24 h post-inoculation, and was greater in sows that developed clinical signs of mastitis." (PMID 29946552, 2018). "Experimental bovine udder challenge with S. aureus isolate 1027 (subclinical mastitis) has shown that there is an immune response by one hour after pathogen challenge, with up-regulation of expression of CCL20, CXCL8, TNF and IL-6 in the teat cistern." (PMID 29705830, 2018). "Epithelia derived from bovine mammary glands with mastitis evidently express proinflammatory cytokines, such as TNF-α and IL-6." (PMID 29686530, 2018). "Indirubin inhibited the expression of IL-1β, IL-6, and TNF-α in LPS-induced mouse mastitis in a dose-dependent manner." (PMID 28255203, 2017). "We analyzed the anti-inflammatory effects of Se on S. aureus mastitis by determining protein and mRNA levels of TNF-α, IL-1β, IL-6 and IL-10 by ELISA and qRT-PCR, respectively." (PMID 29340029, 2017). "S. aureus-induced mastitis is related to many types of inflammatory cytokines such as TNF-α, IL-1β and IL-6." (PMID 28415707, 2017). "IL-1β, IL-6, and TNF-α expression significantly increased after LPS stimulation both in MMEC and in the mouse mastitis model." (PMID 28255203, 2017). "IL-6 and TNF-α are the two most predominant proinflammatory cytokines during the acute phase responses of mastitis." (PMID 27433029, 2016).
mastitis (continued). "In heat-inactivated E. coli challenged bMECs, significant increases of IL-6 and TNF-α gene expression were observed, a finding consistent with a previous study using a different mastitis strain of E. coli." (PMID 27433029, 2016). "The mRNA expression of genes responsible for the inflammatory response (TLR4, LBP, IL-1β, IL-6, IL-8, NF-κB and TNF-α) was significantly increased, consistent with the results of exogenous LPS-induced mastitis by infusion." (PMID 26893357, 2016). "Similar to our previously published results, the proinflammatory cytokine expressions (IL-6 and TNF-α) were inhibited by CP treatment following coliform mastitis pathogen challenges (heat-inactivated E. coli as well as endotoxin)." (PMID 27433029, 2016). "All of these mastitis pathogens, except for LTA, lead to significant increases of IL-6 and IL-8 (P < 0.05)." (PMID 27433029, 2016). "TLR2, NOD2, and inflammatory cytokines (TNF-α, IL-1β, IL-6, CXCL1, IL-10, TGF-β1, and IFN-γ) are involved in the response to mastitis induced by S. aureus." (PMID 25990971, 2015). "Additionally, a recent study found that levels of IL-6, IL-1β, TNF-α, and MPO were all increased in mice that developed mastitis due to S. aureus." (PMID 41148692, 2025). "The identification of IL-1α, IL-6, and CXCR1 as key modulators offers promising avenues for the development of molecular biomarkers and genetic selection strategies aimed at enhancing mastitis resistance in dairy herds." (PMID 40453956, 2025). "A recent in vitro study demonstrated that Lactobacillus could inhibit the expression of inflammatory cytokines (such as IL-6, IL-1β, and TNF-α), thereby preventing mastitis." (PMID 41011421, 2025). "Furthermore, in vivo tests indicated that intramammary infusion of L. casei 03 relieved pathological changes, reduced the secretion of IL1β, IL6 and TNFα and MPO activity in the mouse mastitis model." (PMID 38395896, 2024). "Moreover, using PPI network analysis, we determined that TNF, IL-6, IL-1β, CXCL8, and ICAM1 proteins were the main targets of GYS for mastitis treatment." (PMID 38630770, 2024). "Similarly, rosmarinic acid and nuciferine alleviate LPS-induced mastitis by inhibiting the TLR4/MyD88/NF-κB signaling pathway and production of TNF-α, IL-1β, and IL-6 in MMECs." (PMID 39199398, 2024). "In this study, we found that SAMC suppressed the secretion of IL-6 as well as Il6, Tnf, Cxcl1, and Ccl2 mRNA levels induced by LPS in HC11 cells, suggesting that SAMC is a key component of AGE that modulates the immune response in an in vivo mastitis model." (PMID 39609525, 2024). "Therefore, although there is variation in the time since the onset of inflammation in the spontaneous mastitis cases in this study, the correlations among SCC, IL-6, and TNF-α in milk were confirmed because these dynamics are similar during inflammation." (PMID 39872610, 2024). "We have noted an elevated concentration of proinflammatory cytokine—IL-6 in milk but not in serum, in both cows with clinical and subclinical mastitis." (PMID 38612339, 2024). "Kaempferol suppressed phosphorylation of the NF-κB p65 subunit and the degradation of its inhibitor, IκBα, in the NF-κB signal pathway for the treatment of mastitis; this was accompanied by decreased myeloperoxidase (MPO) production and ANGPTL2 expression, as well as a reduction in TNF-α and IL-6." (PMID 38630770, 2024). "In this study, we demonstrated that oral administration of AGE suppressed the LPS-induced immune response in a mastitis mouse model and that SAMC inhibited LPS-induced interleukin-6 production and nuclear factor κB p65 subunit activation in HC11 mammary epithelial cells." (PMID 39609525, 2024). "In contrast to our findings, previous research showed a non-significant rise in IL-2 and IL-6 markers in cows with subclinical mastitis." (PMID 36899749, 2023). "Although some studies have shown that the IL-6/JAK2/STAT3 signaling pathway is related to non-puerperal mastitis, such reports are few." (PMID 37817809, 2023).
mastitis (continued). "LncRNAs such as LOC107133214, LOC104974443 and LOC101906793 can regulate the expression of inflammatory and cell death-related mRNAs such as IL-6, NFKB1 and TNFAIP3 and participate in the process of mastitis through NOD-like receptor, TNF, MAPK and other signaling pathways." (PMID 37845761, 2023). "In summary, in clinical mastitis-affected cows, immunoreactive cell mean counts in milk increased for IL-4, IL-6, IL-12, and IL-17A and remained nearly absent for IL-13." (PMID 35335696, 2022). "Kaempferol can reduce the expression of IL-6 and TNF-α and ANGPTL2 in cells, prevent the occurrence of mastitis in mice, inhibit the phosphorylation of NF-κB P65 subunit and the degradation of IκBα, and play a therapeutic role in mastitis." (PMID 35757473, 2022). "Moreover, the inflammation of the buffalo udder (i.e., clinical and subclinical mastitis) promoted the increase in cytokines (TNF-α, IL-6, IL-1β, and IFN-γ) production, which impaired the reproductive success in this animal." (PMID 36009715, 2022). "In bovine mastitis, IL-6 is considered as an early but nonspecific indicator of various inflammation states, especially in subclinical mastitis." (PMID 35335696, 2022). "The proinflammatory cytokines IL-1β, IL-6, and TNF-α are important in mastitis." (PMID 35624447, 2022). "However, the SCC and SCS are not constant and are influenced by many environmental factors; therefore, in current research, we targeted serum cytokines (IL-6 and IFN-γ) in combination with SCC and SCS as mastitis resistance phenotypic traits." (PMID 36213405, 2022). "IL-6, IL-8, and TNF-α are important pro-inflammatory cytokines involved in mastitis." (PMID 35174140, 2021). "The selection of possible regulated genes (cytokines TNFα, IL-1β, IL-6, IL-10, chemokines CCL20, CXCL8 and antimicrobial effector molecules LAP and S100A9) were adapted from a recent in-vivo study that also focussed on early inflammatory events in mastitis." (PMID 34798884, 2021). "Our research results showed that PE could significantly inhibit the increase in the levels of inflammatory mediators such as TNF-α, IL-6, IL-1β, MPO and iNOS during mastitis." (PMID 34383710, 2021). "A study showed that inflammatory cytokines (IL-6, IL-17, and IFN-γ, TNF-α) could be used as subclinical mastitis indicators, in addition to SCSs and SCCs." (PMID 33202860, 2020). "Furthermore, DNA methylation was found to regulate the expression of bovine immune-related genes, including IL6, IL8, and TLR4, in response to lipopolysaccharide-induced mastitis." (PMID 33193625, 2020). "The expression of IL-6 was higher in plasma cell mastitis (PCM), which indicated that the IL-6/STAT3 pathway could play a key role in the pathogenesis of PCM." (PMID 33202860, 2020). "In addition, based on published literature, we concluded that TLR4, IL-1β, IL-6, TNF-α and MYD88 are key players in NF-κB signaling and also have an essential role in mastitis development." (PMID 32927884, 2020). "Our results show that activation of GPR109A could significantly reduce the expression of N-P65, IL-6, IL-1β, and TNF-α in BMECs, thus inhibiting mastitis." (PMID 32397071, 2020). "The present study demonstrates that berberine hydrochloride exerts anti-inflammatory effects by inhibiting inflammatory cell infiltration, the production of TNF-α, IL-1β, and IL-6, and the activation of the TLR4/NF-κB signaling pathway in a mouse model of mastitis." (PMID 29849710, 2018). "Studies have shown that some plant (like cepharanthine and kaempferol) could attenuate LPS-induced mouse mastitis by suppressing the production of TNF-α, IL-6 and IL-1β." (PMID 29904013, 2018). "We may infer that increased cytokines of IL-6 and TNF-α secreted by activated fibroblasts within mammary stroma during mastitis could cooperate with epithelial cells, recruit leukocytes to alveoli, and promote inflammation." (PMID 27272504, 2016).
mastitis (continued). "Statistical analysis of transcript and protein level expression changes indicated that 10 genes, namely TLR4, MyD88, IL-6, and IL-10, were up-regulated, while, CD14, TNF-α, MD-2, IL-β, NF-κB, and IL-12 were significantly down-regulated in mastitis tissue in comparison with normal tissue." (PMID 25706977, 2015). "In an A. viridans-induced mouse mastitis model, a single 25-μg dose of AVPL significantly reduced bacterial loads in the mammary glands (~2-log10), alleviated mastitis-related pathological symptoms, and decreased inflammatory cytokine levels (TNF-α, IL-1β, and IL-6) in mammary tissues." (PMID 40970331, 2025). "IL-6 has been recognized as an early but non-specific indicator of mastitis." (PMID 38612339, 2024). "Another study looking at the effect of SCFP supplementation on the Streptococcus uberis mastitis challenge in mid-lactation dairy cows found no change in IL-1β or IL-6 concentrations from the time of the Streptococcus uberis challenge up to 9 days post-challenge." (PMID 39595313, 2024). "Similarly, another study reported that Brazilin (isolated from the traditional herbal medicine Caesalpinia sappan L.)suppressed TLR2, TNF-α, IL-1β, and IL-6 levels by inhibiting the TLR2/NF-κB/MAPK signaling pathways in mammary gland tissues, thus preventing S. aureus-induced mastitis." (PMID 39199398, 2024). "When studying the effectiveness of SMP against mastitis, it was found that SMP supplementation could inhibit the activities of myeloperoxidase (MPO) and N-acetyl-β-D-glucosaminidase (NAGase) and reduce the expression of IL-6, IL-1β and TNF-α inflammatory factors in rats with mastitis." (PMID 36937857, 2023). "However, there is no approach for the on-site and rapid detection of IL-6 for the monitoring of mastitis in dairy farm scenarios." (PMID 35407209, 2022). "Moreover, our analyses recommended that besides SCC and SCS, the association of genetic markers could also be considered with the serum cytokines (IL-6, IFN-γ) while selecting genetically mastitis resistance dairy cattle." (PMID 36213405, 2022). "In addition, TLR4, IL-1β, IL-6, TNF-α, MYD88 and NF-κB might be a useful addition as markers in mastitis control strategies." (PMID 32927884, 2020). "The evidence with respect to specific proteins such as lactoferrin is also conflicting where in some studies it is shown to be increased in mothers with mastitis while in others it does not demonstrate an increase, despite an increase in other milk components such as IL-1ß and IL-6." (PMID 31905959, 2019). "This study found that farrerol could improve pathological injury of mammary glands, attenuate the activity of MPO, inhibit the production of pro-inflammatory mediators (TNF-α, IL-6, IL-1β, iNOS and COX-2) and the phosphorylation of AKT, NF-κB p65, p38 and ERK1/2 in LPS-induced mouse mastitis." (PMID 29904013, 2018). "Also, in an LPS-induced mouse mastitis model and in LPS-treated mouse mammary epithelial cells, GLY treatment significantly reduced MPO activity and protein expression of TNF-α, IL-1β, and IL-6." (PMID 27792814, 2016). "The IL-6 concentration in the serum of HE was not significantly different from the serum IL-6 of the entire group of mastitis cows, regardless of whether the inflammation proceeded in a clinical or subclinical form (44.37 pg/mL vs. 78.09 pg/mL; 128.29 pg/mL vs. 78.09 pg/mL, respectively)." (PMID 38612339, 2024). "However, the IL-6 gene was among those genes that were not differentially expressed in healthy vs. mastitis-affected cows suggesting they are not suitable markers or indicators of mastitis." (PMID 35335696, 2022). "The cytokines in serum such as interleukin-4 (IL-4), IL-6, IL-17, tumor necrosis factor-α (TNF-α) and interferon-γ (IFN-γ) also act as indirect indexes in inflammatory conditions, which suggests that beside SCC and SCS, serum cytokines could be considered as crucial indicators for bovine mastitis." (PMID 28101335, 2017).
mastitis (continued). "qRT-PCR and ELISA were performed to measure the levels of IL-6, TNF, and IL-1β in the breast tissue of mice with LPS-induced mastitis, with or without ammonia treatment." (PMID 40370468, 2025). "No significant change in gene expression of IL-2, IL-4, IL-6, IL-8, IL-10, IFN-γ, and TNF-α by real-time PCR in milk among animals without mastitis vs. animals with mastitis was observed." (PMID 35335696, 2022). "In addition to this, the present study found that IL-6, WBC and hs-CRP played significant mediating roles between glycemic abnormality and the severity of non-lactating mastitis." (PMID 40386528, 2025). "Pretreatment with DCA intraperitoneally, but not CA, alleviated S. aureus-induced mastitis, as evidenced by DCA improving mammary injury, mammary S. aureus burden, proinflammatory markers including TNF-α, IL-1β and IL-6 and MPO activity compared with that of the S. aureus group." (PMID 36755021, 2023). "It should be emphasized that the IL-4, IL-6, IL-8 and TNF-α genes were not differentially expressed in any of the conditions studied (p > 0.05), demonstrating that these genes are not good markers or indicators of mastitis under the analyzed conditions." (PMID 21637453, 2009). "For this purpose, the expression of the interleukin 2 (IL-2), IL-4, IL-6, IL-8, IL-10, interferon gamma (IFN-γ) and tumor necrosis factor alpha (TNF-α) genes was investigated in Black and White (BW) Holstein and Gyr cows with and without clinical signs of mastitis." (PMID 21637453, 2009).